SOX14 (SRY-box transcription factor 14)
Description:
Acts as a negative regulator of transcription.
Synonyms: SOX28
Tractability: No criterion of Open Targets' tractability assessment is met for any kind of drug.
Gene: Protein-coding gene on chromosome 3 (137,764,315 to 137,766,334, forward strand). Ensembl gene ENSG00000168875.
Subcellular location: Nucleus
Gene Ontology:
Molecular function: protein binding; sequence-specific double-stranded DNA binding; DNA-binding transcription activator activity, RNA polymerase II-specific; DNA-binding transcription factor activity, RNA polymerase II-specific; RNA polymerase II cis-regulatory region sequence-specific DNA binding; sequence-specific DNA binding; chromatin binding
Biological process: brain development; negative regulation of DNA-templated transcription; negative regulation of transcription by RNA polymerase II; nervous system development; neuron differentiation; positive regulation of transcription by RNA polymerase II; regulation of DNA-templated transcription
Cellular component: chromatin; nucleus; transcription regulator complex
Genetic constraint (gnomAD): Loss-of-function variants: 5 observed, 14.61 expected, observed/expected ratio (o/e) 0.34, 90% interval 0.18 to 0.72. The upper end of that interval is the gene's LOEUF score, 0.72, which puts it in group 2 of 6, group 1 being the genes least tolerant of losing a copy. Missense variants: 270 observed, 349.29 expected, observed/expected ratio (o/e) 0.77, 90% interval 0.7 to 0.86. Synonymous variants: 164 observed, 156.37 expected, observed/expected ratio (o/e) 1.05, 90% interval 0.92 to 1.19.
Homologues: Orthologues: chimpanzee SOX14 (100% identical), dog SOX14 (100% identical), rabbit SOX14 (100% identical), mouse Sox14 (99% identical), rat Sox14 (99% identical), guinea pig SOX14 (99% identical), zebrafish sox14 (90% identical), tropical clawed frog sox14 (89% identical), pig SOX14 (76% identical), Drosophila melanogaster Sox21a (44% identical), Drosophila melanogaster Sox14 (30% identical), Drosophila melanogaster Sox102F (24% identical), and 1 more. Paralogues in human: SOX21 (66% identical), SOX1 (47% identical), SOX2 (47% identical), SOX3 (43% identical), SOX15 (35% identical), SOX8 (33% identical), SOX10 (32% identical), SOX17 (32% identical), SOX7 (31% identical), SOX9 (31% identical), SOX12 (29% identical), SOX18 (29% identical), and 8 more.
Diseases named in the same sentence as SOX14 in open-access papers:
SOX14 is named in the same sentence as 25 diseases in open-access papers, as found by Europe PMC text mining. Sharing a sentence is not in itself a finding about the gene and the disease. The quoted sentences say what the papers report.
cervical carcinoma (8 papers, 2016 to 2025). A carcinoma arising from either the exocervical squamous epithelium or the endocervical glandular epithelium. "SOX14 hypermethylation is associated with cervical cancer and has the potential to be a molecular biomarker for the screening and early diagnosis of cervical cancer." (PMID 34098886, 2021). "Consistently, SOX14 had higher expression in cervical cancer tissues compared to normal tissues, even quite a few samples." (PMID 34098886, 2021). "When the cut-off value was set as 128.45, the sensitivity and specificity of SOX14 hypermethylation in the diagnosis of cervical cancer were 94.12 and 86.46%, respectively." (PMID 34098886, 2021). "The aim of this study was to identify and validate the potential value of SOX14 methylation in the early detection of cervical cancer." (PMID 34098886, 2021). "SOX14 presented hypermethylation in cervical cancers; furthermore, with the optimal cut-off value, the sensitivity and specificity in the differentiation of precancer and cancer were 94.12 and 86.46%, respectively." (PMID 34098886, 2021). "ROC curve analysis showed that SOX14 hypermethylation had good sensitivity (94.12%) for discrimination of cervical cancer patients that would assist for the choice of therapy." (PMID 34098886, 2021). "First, we extracted the data for SOX14 methylation and expression within cervical cancer from The Cancer Genome Atlas (TCGA) database and analysed them via UALCAN, Wanderer, MEXPRESS and LinkedOmics." (PMID 34098886, 2021). "On the other hand, SOX14 showed opposite prognostic values in cervical cancer and leukemia, with anti-tumor and carcinogenic effects, respectively." (PMID 32849822, 2020). "Our analysis revealed that SOX14 induced apoptosis, changed the cell cycle distribution and inhibited the viability of cervical cancer cells in vitro." (PMID 28926586, 2017). "In this paper we elucidated the role of SOX14 in the regulation of malignant properties of cervical carcinoma cells in vitro." (PMID 28926586, 2017). "One group showed that SOX14 can promote proliferation and invasion capacity of cervical cancer cells by activating the Wnt/β-catenin pathway." (PMID 28926586, 2017). "In cervical carcinoma samples it has been shown that the genomic region where SOX14 is located (chromosome 3q23) encompasses several tumor suppressor genes." (PMID 28926586, 2017). "The results presented here advance our understanding of SOX14 as a novel tumor suppressor candidate in cervical cancer cells." (PMID 28926586, 2017). "Recently, it became evident that SOX14 is one of four hypermethylated genes in cervical carcinoma, considered as a tumor suppressor candidate in this type of malignancy." (PMID 28926586, 2017). "QMSP was designed for 5 genes (GFRA1, SLC6A5, SOX1, SOX14, TBX20) and their diagnostic potential was evaluated on scrapings from a large series of cervical cancer patients (n=125: 57 ADC and 68 SCC) and controls with similar age." (PMID 27738327, 2016). "Sox14 promotes the proliferation and invasion of cervical cancer." (PMID 39889187, 2025). "Hence, to further reveal the role of SOX14 methylation in cervical cancer and validate the potential clinical value of SOX14 methylation in the diagnosis of cervical cancer, we combined information from databases and clinical samples." (PMID 34098886, 2021). "Hence,we analysed the different combinations to explore the potential role of SOX14 hypermethylation in the diagnosis and prevention of cervical cancer." (PMID 34098886, 2021). "Thus, the biomarker of SOX14 hypermethylation in cervical cancer moved forward to the validation step." (PMID 34098886, 2021).
cervical carcinoma (continued). "This study advances our understanding about the role of SOX14 and might explain the molecular mechanism by which this transcription factor could exert tumor suppressor properties in cervical carcinoma." (PMID 28926586, 2017). "Recently it has been shown that human SOX14 is methylated in cervical cancer samples from patients." (PMID 28926586, 2017). "In this paper, we have shown that the SOX14 promoter is methylated in a cervical cancer cell line." (PMID 28926586, 2017). "SOX1 and SOX14 are methylation biomarkers applicable for screening of all cervical cancer types." (PMID 27738327, 2016). "Therefore, the aims of this study were to 1) further explore the relationship of SOX14 methylation in cervical cancer using integrated datasets and web tools and 2) validate the potential value of SOX14 methylation in the screening and early diagnosis of cervical cancer." (PMID 34098886, 2021). "RAPH1, SOX14, DPEP1, and UBL4A have a significant role in the invasion or metastasis of breast cancer, cervical cancer, colon cancer, and pancreatic ductal adenocarcinoma, respectively." (PMID 37378426, 2023). "Of the 53 differentially methylated candidates that were found in both ADC and SCC, 20 genes were described previously in literature as being more frequently methylated in cancer, and 6 genes in (squamous-cell) cervical cancer (SOX1, SOX14, ONECUT1 and WT1) or high-grade CIN (GFRA1, SOX1 and TBX20)." (PMID 27738327, 2016). "Compared to the gene panels recently reported by our group the combination of SOX1/SOX14 methylation showed less positive test results, both in scrapings from women without cervical disease and in women with high-grade CIN, but not in women with cervical cancer." (PMID 27738327, 2016).
embryonal carcinoma (2 papers, 2014 to 2017). A non-seminomatous malignant germ cell tumor characterized by the presence of large germ cells with abundant cytoplasm resembling epithelial cells, geographic necrosis, high mitotic activity, and pseudoglandular and pseudopapillary structures formation. "Data presented here provide an insight into SOX14 expression during in vitro neural differentiation of embryonal carcinoma cells and demonstrate the effect of its ectopic expression on protein levels of SOXB members in HeLa cells." (PMID 24637840, 2014). "In the present study we analyzed the expression of SOX14 in human NT2/D1 and mouse P19 pluripotent embryonal carcinoma cells." (PMID 24637840, 2014). "The aim of this study was to analyze SOX14/Sox14 expression during retinoic acid (RA) induced neural differentiation of pluripotent human NT2/D1 and mouse P19 embryonal carcinoma (EC) stem cells, which display properties similar to embryonic stem cells." (PMID 24637840, 2014).
Allergy (1 paper, 2020). An allergy is an immune response or reaction to substances that are usually not harmful. "SOX14 is associated with apoptosis in cancer cells in the sexual reproductive system and is a crucial determinant of allergy development in Drosophila." (PMID 33633772, 2020).
brain tumor (1 paper, 2024). "For instance, a hypo-methylated DMR at the SOX14 gene locus specific for liver cancer compared to controls and brain tumor samples was identified." (PMID 39030196, 2024).
cervical intraepithelial neoplasia (1 paper, 2021). "Eventually, the clinical diagnostic efficacy of SOX14 methylation in the normal, cervical intraepithelial neoplasia, and cancer groups was analysed by ROCAUC." (PMID 34098886, 2021).
cervical squamous cell carcinoma (1 paper, 2021). A squamous cell carcinoma arising from the cervical epithelium. "Pooled analysis demonstrated that SOX14 methylation levels were significantly increased in cervical squamous cell carcinoma and endocervical adenocarcinoma (CESC) compared to normal tissues (P < 0.001)." (PMID 34098886, 2021).
chronic lymphocytic leukaemia (1 paper, 2021). "In addition, analysis of the genome-wide DNA methylation map of chronic lymphocytic leukaemia showed that SOX14 was one of the methylated genes in patients with chronic lymphocytic leukaemia." (PMID 34098886, 2021).
Infertility (1 paper, 2019). "Taken together, our results suggest that Sox14 is critical for Kisspeptin-neuronal development, which likely underlies the infertility of Sox14-KO mice." (PMID 31420539, 2019).
liver cancer (1 paper, 2024). An epithelial or non-epithelial malignant neoplasm that arises from the liver. "Furthermore, high expression of SOX14 in the 371 TCGA liver cancer dataset was associated with poor survival compared to lower expression." (PMID 39030196, 2024).
melanoma (1 paper, 2015). A malignant, usually aggressive tumor composed of atypical, neoplastic melanocytes. "SOX2is regulated by HH signaling where transcriptionfactorsGLI1 and GLI2 directly bind to the proximal promoter region of SOX2 in primary melanoma cells.Also, human SOX14 expression is GLI1 dependent in U87MG cells and SHH dependent in U87MG and HepG2 cells." (PMID 26588701, 2015).
muscular dystrophy (1 paper, 2023). Muscular dystrophy (MD) refers to a group of more than 30 genetic diseases characterized by progressive weakness and degeneration of the skeletal muscles that control movement. "SOX14 R80Q (HMG box location 73/75) was found in two individuals with abnormality of the musculature, one with altered muscle physiology and another with muscular dystrophy." (PMID 36672963, 2023).
virus infection (1 paper, 2024). "Since virus infection is partial and the same skin region can include both abnormal and normal feather follicles, SISH was applied to detect the expression of SOX14 and scale keratin genes in the same skin sections." (PMID 38755126, 2024).
cancer (9 papers, 2014 to 2025). A tumor composed of atypical neoplastic, often pleomorphic cells that invade other tissues. "SOX14 has been shown to influence tumor cell differentiation and epithelial-mesenchymal transition in some cancers." (PMID 40567599, 2025). "As expected, the MSP results demonstrated that the methylation positive rate of SOX14 in cancer tissues (70.59%) was obviously higher than that in normal tissues (5.26%)." (PMID 34098886, 2021). "The CpG-methylation site of SOX14 validated in our study located in the gene body, which showed higher methylation in cancer samples." (PMID 34098886, 2021). "Both the verification and validation cohorts indicated that the methylation level and the positive rate of SOX14 gradually increased with increasing severity from normal to cancer samples (P < 0.01)." (PMID 34098886, 2021). "SOX14, a transcription factor, has largely been unexplored in cancer." (PMID 36389725, 2022). "The YI was 0.81, which indicated that SOX14 was a cancer-related biomarker." (PMID 34098886, 2021). "Except for TBX5, all 5 genes (GFRA1, SLC6A5, SOX1, SOX14 and TBX20) were significantly differentially methylated between normal and cancer tissues with a high methylation frequency in both ADC and SCC." (PMID 27738327, 2016). "In the second diagnostic evaluation 229 scrapings were analyzed for SLC6A5, SOX1, SOX14 and TBX20 hypermethylation using the QMSP threshold values that were set in the normal and cancer samples." (PMID 27738327, 2016). "In contrast, studies have shown that gene methylation is associated with the sensitivity of cancer to definitive chemoradiotherapy (CRT), while SOX14 did not present this association." (PMID 34098886, 2021). "Similarly, the SOX14 methylation positive rate increased from the normal to cancer samples and were 48.15% (13/27) in the normal samples, 72.22% (26/36) in CINII, 90.91% (30/33) in CINIII, and 100% (17/17) in cancer, respectively." (PMID 34098886, 2021).
tumor (4 papers, 2017 to 2025). "What’s more, consistent with studies that have revealed that DNA methylation occurs in a tissue-specific, cell type-specific and stage-specific manner,SOX14 methylation correlated with tumour histological type in our analysis." (PMID 34098886, 2021). "These showed that, SOX14 cannot exert its potential tumor-suppressive role due to hypermethylation." (PMID 28926586, 2017).
infection (2 papers, 2016 to 2022). The state of being infected such as from the introduction of a foreign agent such as serum, vaccine, antigenic substance or organism. "For this purpose, we applied the modified rabies virus technology, guiding primary infection of a glycoprotein-deleted, GFP-expressing and avian-pseudotyped rabies (SADB19 ΔG-eGFP, EnvA; in short RVdG) to the Sox14 neurons of the IGL/LGv." (PMID 36280260, 2022).
genetic disorders (1 paper, 2014). "To date, no SOX14/Sox14 mutations associated with human genetic disorders or animal phenotypes have been described." (PMID 24637840, 2014).
SOX14 also shares sentences with these, for which no sentence is quoted: breast carcinoma (1 paper); campomelic dysplasia (1); cervical adenocarcinoma (1); cervical disease (1); colon cancer (1); endocervical adenocarcinoma (1); leukemia (1); pancreatic ductal adenocarcinoma (1); Stroke (1).